CD4 (CD4 molecule)
Diseases named in the same sentence as CD4 in open-access papers (continued):
Sharing a sentence is not in itself a finding about the gene and the disease.
infection (continued). "In HOS CD4+/CCR5+ cells, DTNB exposure potently reduced infection by HIV-1JR-FL or HIV-1AD8 Env-pseudotyped virions without impairing cell viability (trypan blue exclusion test)." (PMID 23206338, 2012). "We then combined the CD4+ and CD8+ T cells at different ratios for 3 days to suppress the infection." (PMID 22792231, 2012). "CD4+ T cell count and pVL were monitored in PHI patients from the first month up to 4 years after infection." (PMID 23236388, 2012). "Animals that do not control bacterial replication had an overall increase in CD4+ and CD8+ cells that was similar to the response observed at day 7 after infection." (PMID 22428026, 2012). "Our results provide a method for direct quantification of HIV DNA turnover during active infection, and show for the first time that SIV DNA turnover in resting CD4+ T cells is strongly correlated with viral load during chronic infection." (PMID 22496643, 2012). "Although IFN-γ and IL-10 can be produced by many cell types, includingB cells, macrophages, and CD4+ or CD8+ T cells, the CD4+T cell mediated immune response plays a central role in the control of schistosomaafter natural infection or vaccination." (PMID 22802961, 2012). "In order to directly compare the role of OX40 during acute and persistent LCMV infection, we performed co-transfer experiments with WT and OX40−/− TCRtg CD4 and CD8 T cells prior to LCMV Armstrong and cl13 infection." (PMID 22969431, 2012). "CD4+ T-cells specific for HIV versus CMV preferentially express gut-homing markers: HIV preferentially infects HIV-specific CD4+ T-cells, while CMV-specific CD4+ T-cells are relatively resistant to infection in vivo." (PMID 22470433, 2012). "The infection of HIV-1 Vpr+ was robust in the highly permissive, activated PBMCs and CD4+ T-cells and the peak of luciferase expression was reached at 3 days post-infection (dpi) and declined sharply at 5 dpi." (PMID 22570689, 2012). "At the time of clinical presentation and ALT elevation, vigorous proliferation of HCV-specific CD4+ T cells with concomitant IL-2 and IFN-γ production is readily detectable in the blood of patients who later recover and clear the infection." (PMID 22754568, 2012). "Then, this cytolytic infection induces the activation of T cells, and MDV establishes latency in a part of the activated CD4+ T cells at 1–2 weeks after infection." (PMID 22612856, 2012). "It is already known from BDV infection of rats that the route of infection determines the severity of disease and that an early up-regulation of BDV-specific CD4 T cells can efficiently protect against infection by the virus." (PMID 22304809, 2012). "These primary CD4+ T cells were activated and infected with infectious HIV-1 and treated with cocaine after infection." (PMID 23251514, 2012). "From the obtained results in the presented figures, it is clear that in the primary stage of the infection with the (HIV) virus, a dramatically decrease in the level of the CD4+ T-cells occurs because of the death of such infected cells." (PMID 22214194, 2012). "The percentage of CD4+ T cells was higher in yellow cattle, while the percentage of CD8+ T cells was higher in water buffalo from pre-infection to 7 w post infection." (PMID 22414188, 2012). "In attempts to focus more deeply on the impact of MT or BT infection on the T-cell cytokine pattern, we have characterized the frequency of TNF-α+, IFN-γ+ and IL-10+ T-cells as their major subsets (CD4+ and CD8+) within splenocytes." (PMID 22412949, 2012). "Women also have higher amounts of serum antibodies, CD4+ T cells and CD4/CD8 T cell ratios in blood, along with higher cytokine expression during infection and stronger T cell humoral immune responses." (PMID 23251558, 2012).
infection (continued). "However, little in vivo data are available on the dynamics of Th17 cells, another important CD4+ T cell subset, after Schistosoma japonicum infection or whether these cells and their defining IL-17 cytokine mediate host protective responses early in infection." (PMID 22102924, 2011). "Using an antibody depletion strategy with anti-CD4 and anti-CD8, they showed that both CD4 and CD8 T cells were important for control of infection with CD8 T cells playing the dominant role." (PMID 21687650, 2011). "To address this, we examined the proportion of CD4+CD25+CD127low Treg in PB and LN of SHIV challenged RM during early infection." (PMID 21483689, 2011). "B7-H1 and PD-1 expression was assessed on CD4+ and CD8+ T cells isolated from the CNS to determine their potential role in regulation of CNS-infiltrating effector T cell function at the site of infection." (PMID 21494618, 2011). "Significantly, over 30% of CD4+ T cells, 25% of CD8+ T cells, 40% of CD3−NK1.1+ NK cells and CD3+NK1.1+ NKT cells were IFN-γ+ at day 7 after infection." (PMID 22206036, 2011). "Our data demonstrate a progressive increase in the percentage of CD4+CD25+ T cells during P. chabaudi infection, with a peak observed on day 4 after infection." (PMID 21464982, 2011). "We infected CCL19-treated CD4+ T-cells with WT NL4.3 and NL4.3Δenv to determine if spreading infection contributed to the high levels of integrated HIV observed following infection of CCL19-treated CD4+ T-cells." (PMID 21992606, 2011). "Given this unique early dependence on CD4 help, we evaluated the effects of CD4+ cells on the development of functional properties of CD8+ T cells and on their ability to abolish infection." (PMID 21245909, 2011). "Our findings indicate that CNS TB in pediatric patients increases the sensitivity of CD4 and CD8+/CD28+ T cells to apoptosis, suggesting a hypoergic status of this infection." (PMID 22111973, 2011). "Silencing ADAM10 expression with small interfering RNA (siRNA) 48 hours before infection significantly inhibited HIV-1 replication in primary human monocyte-derived macrophages and in CD4+ cell lines." (PMID 21569301, 2011). "Recently, the transcriptional profiling of CD4+ and CD8+ T cells from early infection, chronic infection, and LTNP patients has been reported." (PMID 21410942, 2011). "It is possible that partial down regulations of both CD4 and CXCR4 result in a synergistic effect to achieve the potent inhibition of NL4-3 infection of MT4 cells." (PMID 22039528, 2011). "We observed specific alterations in the abundance of CD4+/CCR5+ and CD4+/CXCR4+ T-cells, and concentrations of immune proteins across different HIV clades and as infection progresses." (PMID 21655330, 2011). "HSV-specific CD4+ T-cells migrate into infected vaginal tissue and produce IFN-γ, with peak responses occurring 4–5 days after infection." (PMID 21283640, 2011). "Following infection with 200 Trichuris eggs (high dose), wild-type C57BL/6 (WT) mice develop a polarized CD4+ Th2 cell response characterized by high levels of IL-4, IL-5 and IL-13." (PMID 21573179, 2011). "Pre-existing MHC-II/peptide complexes were assayed with EBNA1-specific ‘SNP’ CD4+ effector T cells to detect EBNA1 antigen that is expressed in both the latent and lytic phases of infection in EBV-transformed B lymphoblastoid cell lines (LCL)." (PMID 22216005, 2011). "Although circulating T cells lack CD69 expression in normal macaques, both CD4+ and CD8+ T cells expressing CD69 increased in blood 10 days after SIV-infection." (PMID 22096538, 2011). "To determine if there was production of any infectious virus in CCL19-treated infected CD4+ T-cells, we infected cells with either WT NL4.3 or NL4.3Δenv and collected supernatants at day 4 following infection." (PMID 21992606, 2011). "An efficient cellular immune response with IFNγ-secreting CD4+ and CD8+ T cells is responsible for the decrease of P. brasiliensis in the organs during experimental infection." (PMID 21249212, 2011).
infection (continued). "2W:I-Ab tetramer staining and magnetic bead enrichment was used to characterize 2W:I-Ab+ CD4+ T cells from NALT and other lymphoid tissues after intranasal GAS-2W infection." (PMID 21966268, 2011). "DC express an array of receptors including the surface proteins CD4 and CCR5/CXCR4, which are the main receptors utilized by HIV-1 for infection of immune cells." (PMID 21853149, 2011). "Co-expression of DC-SIGN with CD4 and CCR5 in transfected cell lines or in T cell lines resulted in modest (two- to five-fold) increases in infection with HIV-1 although the relative enhancement was increased in cell lines that expressed lower levels of CCR5." (PMID 22163292, 2011). "After infection, the MFI of CD4 on DCs subsets showed a tendency to decrease, while that of CCR5 showed a contrary tendency to increase." (PMID 22174949, 2011). "This role appears to be independent of CD4+ T cell-mediated adaptive immune responses and may be a result of the reduced ability of macrophages to engulf Cmu and an increased susceptibility of pulmonary epithelial cells to infection." (PMID 21573182, 2011). "Purified CD4+CD25+ mLN cells (2.5×106, >90% purity) from mice at the chronic stage of infection were administered to hCD2-VaDsRed-B.6 mice co-incident with the onset of egg deposition." (PMID 21858239, 2011). "Although the effect of DC-SIGN was to increase infection by both CD4-dependent and CD4-independent strains of HIV, the level of enhancement was consistently lower for the CD4-independent strain." (PMID 22163292, 2011). "Identifying early predictors of infection outcome is important for the clinical management of HIV infection, and both viral load and CD4+ T cell level have been found to be useful predictors of subsequent disease progression." (PMID 21359149, 2011). "The role of both naturally occurring CD4+CD25+Tregs and interleukin (IL)-10-secreting Tregs in infection has been the subject of several excellent recent reviews." (PMID 21698274, 2011). "However, because cathepsin B clearly had an inhibitory effect on the CD4-independent infection and because cathepsin B activity in 293T cells is extremely low, 293T cells could have another factor(s) suppressing cathepsin B activity that is not expressed in HeLa cells." (PMID 21541353, 2011). "Given that CD4 T cells also produce RANTES, it is possible that CD4 T cells are an important source of RANTES during LCMV clone 13 infection but that remains to be determined." (PMID 21814510, 2011). "CD4+ T cells are necessary to generate a CD8+ CTL response and viral clearance after infection with HSV." (PMID 21569289, 2011). "At most of the days, the CD4 and CCR5 expressed on pDCs showed significant changes, when compared with that during pre-infection." (PMID 22174949, 2011). "Our results illustrate the cost-effectiveness of testing for HIV infection in settings where diagnosis at higher CD4 counts early in the course of disease is likely to occur and when treatment with HAART is initiated earlier in the course of infection." (PMID 21625489, 2011). "HeLa cells modified to stably express CD4 and CCR5 (TZM-bl cells) were screened with siRNAs targeting genes trapped with reovirus, influenza A, or Marburg virus 48 h prior to infection with LAV (X4-tropic)." (PMID 21569301, 2011). "The density of susceptible cells in healthy tissue is an upper limit to infected cell densities in very early infection, before the influx of SIV-specific CD4 cells that provide new targets." (PMID 22125483, 2011). "Marked declines in CD4+CD69+ T cells were observed in jejunum (P<0.0001) and mesenteric lymph node (P = 0.002) by 13 days of infection and declined thereafter throughout infection." (PMID 22096538, 2011). "In our assays, after pretreatment of the HeLa-CD4-LTR-β-gal cells and bDLE removal prior to viral challenge, protection against infection lasted 7 hours after bDLE was removed from the extracellular compartment." (PMID 22044844, 2011).
infection (continued). "Reduced expression of CCR5 on target CD4+ cells lowers theirsusceptibility to infection by R5-tropic HIV-1, potentially preventingtransmission of infection and delaying disease progression." (PMID 21647388, 2011). "B6, CD4-/- and MHCII-/- mice were infected with Δm04Δm06Δm152 MCMV and its parental BAC-derived virus and viral titers were examined 28 days post infection in the SG." (PMID 21901102, 2011). "During TMEV infection, CNS-infiltrating CD4+ and CD8+ T cells express increased levels of B7-H1 and PD-1 at day 7 post-infection, though CD8+ T cells display significantly higher levels." (PMID 21494618, 2011). "While it has been demonstrated that extralymphoid CD4+ T cells can directly respond to secondary infection, little is known about how rapidly this response is initiated, and how early activation of T cells in the tissue may affect the innate response to infection." (PMID 21647373, 2011). "Ongoing studies in our laboratory are designed to characterize the transcriptional profiles of CD4+, CD8+ and other intestinal lymphocyte subpopulations following primary and secondary infection with the different coccidia species." (PMID 22140460, 2011). "This increase persisted when the cells transited into the memory compartment, as frequency of LCMV-specific CD4+ and CD8+ T cells remained higher in mutant mice by 50 days after infection." (PMID 21455314, 2011). "Intracellular expression of cytokines TNF-α, IL-2, and IFN-γ was determined in popliteal lymph node CD4+ and CD8+ T cells during acute FIV infection in controland CD25 depleted cats." (PMID 21364928, 2011). "On the other hand, CD4+ Tregs down-regulate the immune responses of CD4+ Th cells and CD8+ CTLs thus, prolonging the recovery from acute FV infection, and allowing the establishment of a chronic infection." (PMID 21943070, 2011). "In other words, during the first year of infection, the CD4 cell count in an HIV controller with 900 CD4 cells/ml at HIV diagnosis fell to 890 CD4/mm3 [95%CI: 885.0–899.4], representing a mean decline of 10 CD4/mm3." (PMID 21533035, 2011). "Levels of T cell activation were already significantly higher in SIVmac251-infected macaques at 7 days (p<0.001 for CD3+; p<0.001 for CD4+ and p<0.05 for CD8+ T cells) and 21 days post infection (p<0.01 for CD3+; p<0.05 for both CD4+ and CD8+ T cells)." (PMID 21464951, 2011). "Surprisingly, in CD4-/- mice, MCMV replication in the SG was eventually controlled between 200 to 400 days post infection." (PMID 21901102, 2011). "Previous reports of T cell dynamics in the GALT of rhesus macaques, following infection with attenuated SIV, suggested that minimal changes occurred since the total CD4+population remained unaltered." (PMID 21291552, 2011). "Titration on cell lines expressing different levels of CD4 and CCR5 demonstrated efficient infection of cells with variable levels of these molecules." (PMID 21843318, 2011). "After excluding 7 participants from the recent infection group (1 with CD4<200 cells/μl and 6 missing CD4 results), 20 women or 12.4% of HIV-positive VCT clients were classified as having a recent infection by both the BED-CEIA and AI assays." (PMID 21949704, 2011). "Prior to infection, MLNs of ΔdblGATA-1 mice contained significantly more GFP+ CD4+ CD62Llow T cells compared to 4get MLNs." (PMID 21155838, 2011). "The percentage of spleen CD4+ and CD8+ T cells that proliferated in response to PPD or Mtb stimulation was relatively low at 4 weeks and increased significantly at 8 weeks of infection (p = 0.01)." (PMID 22645653, 2011). "In vitro infection experiments to compare DC-SIGN enhancement of CD4-dependent and CD4-independent strains demonstrated significantly lower enhancement of the CD4-independent strain." (PMID 22163292, 2011). "This is commonly explained by the fact that CD4+ T cells play an important role in immune control, providing help for both antibodies and CD8+ T cells responses, which act to control infection." (PMID 21359149, 2011).
infection (continued). "HIV-1 RNA <50 copies/mL, CD4% or count, age, and receiving HAART promoted a recent infection result." (PMID 21943091, 2011). "Dendritic cells (DCs) connect innate and adaptive immunity, and are necessary for an efficient CD4+ and CD8+ T cell response after infection with Mycobacterium tuberculosis (Mtb)." (PMID 22024399, 2011). "Subsequently, the mean fluorescence intensities (MFI) of CD4 and CCR5 expressed on both CD1c+ mDCs and pDCs were observed during the acute SIVmac239 infection." (PMID 22174949, 2011). "While the proportion of CD4+ T cells proliferating ex vivo decreased at later time points, CD8+ T-cell proliferative capacity remained at the same level up to 16 weeks of infection." (PMID 22645653, 2011). "Further, marked, selective depletion of intestinal CD4+CD69+ T cells occurred in early SIV infection, and this depletion persisted throughout infection." (PMID 22096538, 2011). "The mean fold increase of US RNA (expression at day 4 compared to day 0) following infection of PHA/IL-2 activated, CCL19-treated and unactivated CD4+ T-cells was 21.1, 1.1 and 0.5 fold respectively (n = 5; p < 0.05 for all comparisons)." (PMID 21992606, 2011). "This cytokine induction was accompanied by the markedly enhanced recruitment of activated CD4+ T cells, macrophages, and DCs in animals treated with TLR agonists fueling the initial foyer of infection." (PMID 21852945, 2011). "The kinetics of viral replication and the nature of the antiviral immune response in experimentally infected humans and macaques are similar, as strain-specific CD4+ and CD8+ T cell and antibody responses arise within 14 days of infection." (PMID 21747924, 2011). "In the case of transitory infection, T cell activation is critical to support HIV replication and also promotes T cell traffic that carries infected and uninfected target CD4+ T cells into the meninges and perivascular spaces." (PMID 21569420, 2011). "By contrast, in infection with CCR5-tropic viruses, it is unclear which CD4+ T cell population is ideal to study in order to understand target cell availability." (PMID 21152101, 2010). "First, we showed that trypomastigotes induce IL-17 production by CD4+, CD8+, and NK cells from naïve mice, and that an increased number of IL-17+ cells is observed during the acute phase of infection." (PMID 20169058, 2010). "In human and macaque gastrointestinal mucosa, most attention has been focused on the small intestine, where lamina propria CD4+ T cells are prominent HIV-1 and SIV target cells and undergo profound depletion shortly after infection." (PMID 20380696, 2010). "Human CD4+ T-lymphoid SupT1 cells were preincubated with the compounds for 6 h, infected with the HIV-1 vector at a multiplicity of infection (MOI) of ∼0.05 and analyzed by flow cytometry 24 h later." (PMID 20486932, 2010). "Incubation of the virus with CEM-SS cells which expresses CD4, CXCR4, ICAM-3 and MHC class II molecules results in the latter forming syncitia upon infection." (PMID 20946627, 2010). "Co-incubation with Cc-CD4 also varied depending on the reference HIV-1 clone and effectively blocked from 22–56% of infection." (PMID 20442778, 2010). "Moreover, an essential role for CD4+ T cells in host defense during persistent infection in resistant mice is further supported by the sharp increase in overall percentage and activation of these cells which coincides with reductions in Salmonella bacterial burden beginning week 3 post-infection." (PMID 20714351, 2010). "Infection by HIV-1, a member of the genus Lentiviridae, results in an acute period characterized by high viral loads and a transient drop in CD4+ T cell counts." (PMID 21552427, 2010). "CD4 and NKT cells levels were significantly higher in C57Bl/6 mice compared to Balb/c mice at d15 post-infection." (PMID 20625554, 2010).